PPP1R1C (protein phosphatase 1 regulatory inhibitor subunit 1C)
Description:
May increase cell susceptibility to TNF-induced apoptosis.
Synonyms: IPP5; Inhibitor-1-like
Tractability: No criterion of Open Targets' tractability assessment is met for any kind of drug.
Gene: Protein-coding gene on chromosome 2 (181,954,241 to 182,131,398, forward strand). Ensembl gene ENSG00000150722.
Subcellular location: Cytoplasm
Subcellular location (Human Protein Atlas): Nucleoplasm; Golgi apparatus; Nucleoli
Gene Ontology:
Molecular function: protein binding; protein phosphatase inhibitor activity
Biological process: intracellular signal transduction; signal transduction
Cellular component: cytoplasm
Genetic constraint (gnomAD): Loss-of-function variants: 5 observed, 6.16 expected, observed/expected ratio (o/e) 0.81, 90% interval 0.42 to 1.63. That is too few expected variants to judge how well the gene tolerates losing a copy. Missense variants: 81 observed, 76.32 expected, observed/expected ratio (o/e) 1.06, 90% interval 0.89 to 1.28. Synonymous variants: 22 observed, 25.5 expected, observed/expected ratio (o/e) 0.86, 90% interval 0.62 to 1.23.
Homologues: Orthologues: chimpanzee PPP1R1C (99% identical), macaque PPP1R1C (94% identical), rabbit PPP1R1C (92% identical), guinea pig PPP1R1C (91% identical), pig PPP1R1C (91% identical), rat Ppp1r1c (86% identical), mouse Ppp1r1c (84% identical), dog PPP1R1C (70% identical), tropical clawed frog ppp1r1c (70% identical), zebrafish ppp1r1c (53% identical). Paralogues in human: PPP1R1A (47% identical), PPP1R1B (39% identical).
Diseases named in the same sentence as PPP1R1C in open-access papers:
PPP1R1C is named in the same sentence as 7 diseases in open-access papers, as found by Europe PMC text mining. Sharing a sentence is not in itself a finding about the gene and the disease. The quoted sentences say what the papers report.
glioblastoma (4 papers, 2017 to 2023). The most malignant astrocytic tumor (WHO grade IV). "Another study focused on the tumor suppressive effect of miR-182 in glioblastoma showed that miR-182 overexpression diminished in vivo and in vitro glioblastoma tumorigenesis by targeting Protein phosphatase 1 regulatory inhibitor subunit 1 C (PPP1R1C)." (PMID 37438760, 2023). "In glioblastoma, miR-182-5p targets protein phosphatase 1 regulatory inhibitor subunit 1C." (PMID 31007608, 2019). "PPP1R1C protein and RNA expression as assessed by tissue microarray and quantitative real time PCR, respectively, was inversely correlated to miR-182 expression in glioblastoma patients and in the metastatic glioblastoma cell line U87-MG." (PMID 29383111, 2017). "PPP1R1C acts as an oncogene in glioblastoma, the high expression of which was shown to participate in cell proliferation, migration, and invasion and the Temozolomide (TMZ) chemosensitivity of glioblastoma patients." (PMID 37438760, 2023). "We initially evaluated relative miR-182 and PPP1R1C expressions in the glioblastoma cell line U87-MG and the non-malignant HCN-2 cell line." (PMID 29383111, 2017).
cervical cancer (1 paper, 2017). A primary or metastatic malignant neoplasm involving the cervix. "It will also be of potential interest to study if miR-182 mediated control of PPP1R1C is also functionally important in cervical cancer pathogenesis." (PMID 29383111, 2017).
tumor (4 papers, 2016 to 2023). "Another upregulated (1.78-FC) gene of interest was PPP1R1C, and increased expression may increase tumor cell susceptibility to TNF-induced apoptosis." (PMID 37446056, 2023). "Increased Prkar2a expression, related to a low-oxygen/high-altitude adaptation, was observed in the hearts of Tibetan pigs in comparison to low-land pigs, while the expression of Ppp1r1c has been studied only in tumor hypoxia." (PMID 38304737, 2023). "The PPP1R1C (protein phosphatase 1 regulatory inhibitor subunit 1C) gene possesses antiproliferative and tumour-suppressive functions." (PMID 36197921, 2022).
cancer (3 papers, 2017 to 2023). A tumor composed of atypical neoplastic, often pleomorphic cells that invade other tissues. "Several DEGs identified were known to be involved in several cancers, these include the microRNA MIR-186 and the PPP1R1C genes, both of which were up-regulated in our study, and NGEF, C9orf163, INKA2-AS1 and SULT2B1 which were found to be downregulated." (PMID 36197921, 2022). "Not a lot is known about function of PPP1R1C in normal brain tissue or in cancer." (PMID 29383111, 2017).
PPP1R1C also shares sentences with these, for which no sentence is quoted: alcohol dependence (1 paper); breast carcinoma (1); leukoplakia (1).